INSR (insulin receptor)
Diseases named in the same sentence as INSR in open-access papers (continued):
Sharing a sentence is not in itself a finding about the gene and the disease.
Insulin resistance (continued). "Downregulation of the number and expression of insulin receptor causes insulin resistance and inhibition of the various physiological effects of insulin, including its vasoactive effect." (PMID 21801458, 2011). "To determine the role of insulin action in macrophages and monocytes in obesity-associated insulin resistance, we conditionally inactivated the insulin receptor (IR) gene in myeloid lineage cells in mice (IRΔmyel-mice)." (PMID 20463885, 2010). "Taken together, these data reveal that myeloid cell-restricted insulin receptor deficiency leads to striking protection from obesity-induced insulin resistance." (PMID 20463885, 2010). "The ER stress, in turn, led to the suppression of insulin receptor signaling, causing hepatic insulin resistance and an enhanced TG synthesis." (PMID 20307304, 2010). "Question 1: Do variations in genes encoding the insulin receptor substrates -1 and -2 and/or genes encoding the glucose transporter proteins predict salt-induced insulin resistance in Dahl S rats?" (PMID 18570670, 2008). "For example, mutations in the insulin receptor can lead to severe insulin resistance and clinical defects such as leprechaunism." (PMID 19007436, 2008). "This factor is also part of nucleoprotein complex controlling human insulin receptor gene transcription and its loss causes insulin resistance and diabetes in human and mice." (PMID 17645789, 2007). "One explanation is that, while patients homozygous for INSR LOF variants present with severe insulin resistance, those heterozygous are generally asymptomatic, and heterozygous impairment of INSR expression protects from and reverses diet-induced hepatic steatosis in mice." (PMID 40065360, 2025). "Although our study did not include direct measurements of insulin levels or androgen profiles, the genotype–phenotype correlation is biologically plausible, supported by extensive literature linking INSR gene variants to insulin resistance and hyperandrogenic symptoms." (PMID 40725495, 2025). "Indeed, although InsR levels in T2DM models are reduced by approximately 90%, both defects in InsR and downstream signaling are implicated in the development of insulin resistance." (PMID 39966707, 2025). "Notably, Nrf2 deficiency in HCV-infected cells downregulates insulin receptor expression, establishing a direct link to insulin resistance." (PMID 40918255, 2025). "Brain insulin resistance, defined as deficient insulin effect transmission due to reduced insulin receptor (IR) density or impaired cellular signaling pathway, has also been described in the context of AD progression, existing independently of peripheral insulin sensitivity." (PMID 40430434, 2025). "MASLD-promoting variants in INSR are associated with increased hepatic insulin resistance." (PMID 39774697, 2025). "Genetic variations in the INSR gene have been shown to be associated with insulin resistance, which may lead to a predisposition to PCOS8." (PMID 40105555, 2025). "Subsequent studies confirmed that insulin resistance in patients with ALS may be associated with reduced InsR expression." (PMID 38818523, 2024). "Besides, the over activation of JNK during sustained ERS promotes serine phosphorylation and inhibits tyrosine phosphorylation of IRS-1, which consequently causes inhibition of insulin receptor signaling and insulin resistance." (PMID 40302954, 2024). "Furthermore, excess c-Jun N-terminal kinase (JNK) can lead to insulin resistance through its effect on the intracellular signaling pathway causing deactivation of insulin receptor." (PMID 38962375, 2024). "While impaired insulin receptor function at the skeletal muscle causes hyperinsulinemia and decreased peripheral glycogen formation from insulin resistance, preserved receptor function in the liver provokes hypoglycemia by suppressing glucose production in the setting of hyperinsulinemia." (PMID 39483531, 2024).
Insulin resistance (continued). "On the other hand, the downregulation of insulin receptor phosphorylation levels in the case of long-term hyperinsulinemia decreases insulin sensitivity, which may also contribute to the insulin resistance caused by long-term chronic hyperinsulinemia." (PMID 38334891, 2024). "Galectin-3 binds to the insulin receptor and causes insulin resistance." (PMID 37738450, 2024). "To examine whether insulin resistance at a whole-body level leads to accelerated atherosclerosis, we generated mice with haploinsufficiency of the insulin receptor (IR+/−), deficient in Apolipoprotein E (ApoE−/−) and fed them a Western diet for 12 weeks." (PMID 39401163, 2024). "The increased MMP-8 may promote weight gain and insulin resistance in obese individuals by cleaving and degrading the human insulin receptor, making obese patients more susceptible to atherosclerosis and increasing long-term mortality." (PMID 39609876, 2024). "Haploinsufficiency of the gene encoding for β2-chimaerin (CHN2) in combination with the insulin receptor gene (INSR) was detected in a family with insulin resistance and early diabetes onset, being one of the few examples of the digenic cause of disease in diabetic patients." (PMID 39598690, 2024). "One of the consequences of NADPH oxidase NOX2 activation is that increased ROS production can lead to insulin resistance by affecting insulin receptor signal transduction, causing a decrease in GLUT4 transporter expression and thus glucose uptake, thereby contributing to hyperinsulinemia." (PMID 37718435, 2023). "In addition, some insulin‐signaling proteins, such as p70S6K, p‐GSK3β, p‐Akt, and p‐insulin receptor, are contained in serum sEVs, indicating its association with incidences of insulin resistance." (PMID 37593852, 2023). "Indeed, e.g., an age-associated cholesterol reduction triggers brain insulin resistance by facilitating ligand-independent receptor activation, while activation of InsR and IGF1R depends critically on the structures of membrane sterols." (PMID 36835322, 2023). "Rare mutations in the insulin receptor protein coding sequence can give rise to severe growth defects and insulin resistance, while changes in the expression and regulation of INSR can affect overall signalling and has been associated with diabetes, cancer, and neurodegenerative diseases." (PMID 37621079, 2023). "It is widely known that, in obesity, chronic low-grade inflammation and a disturbed balance between oxidative stress and the antioxidant defense system are significant in the inhibition of the insulin receptor signaling cascade and strongly associated with insulin resistance and type 2 diabetes." (PMID 36978903, 2023). "These events not only disrupt insulin receptor signaling cascades and promote insulin resistance but also are associated with the development of hepatic steatosis and muscle dysfunction and may trigger the development of sarcopenia." (PMID 36875140, 2023). "In addition, BCAAs can continuously activate mTOR signal and damage insulin signal transduction through insulin receptor substrate, and abnormal BCAAs metabolism can cause the accumulation of BCAAs metabolites and eventually lead to insulin resistance." (PMID 36824437, 2023). "Insulin resistance is associated with reduced cortical insulin receptor activation, impaired clearance of amyloid-β (Aβ) oligomers, increased cerebral abnormal neurotic plaque burden, and the cerebral microvascular dysfunction which is associated with memory loss or decline of cognition." (PMID 36776436, 2023). "These shrunk adipose tissues in BRSK2-overexpressing mice might be attributed to the acute insulin resistance caused by massive insulin secretion, consistent with the phenomenon caused by the insulin receptor antagonist S961." (PMID 37188647, 2023). "Deficient INSR gene processing may impair insulin biological responses, ultimately causing insulin resistance and glucose intolerance." (PMID 37894381, 2023).
Insulin resistance (continued). "By suppressing neuroinflammation, simufilam may also reduce insulin resistance associated with AD: neuroinflammation in both AD and obesity or type 2 diabetes induces insulin resistance and insulin receptor dysfunction." (PMID 37762230, 2023). "Likewise, overexpression of PDGF increased the risk for T2DM, hyperglycemia, as well as insulin resistance by decreasing the insulin receptor and insulin receptor substrate 1 (IRS-1) protein abundance." (PMID 36292250, 2022). "The primary focus of this investigation was to examine altered upstream intracellular factors, mainly signaling through the insulin receptor and insulin receptor substrate in the gastrocnemius muscle of OZRs that may cause insulin resistance." (PMID 36547071, 2022). "Moreover, the long-term use of insulin increases insulin receptor sensitivity and causes insulin resistance." (PMID 36422117, 2022). "Furthermore, using LIRKO mouse as a model of pure insulin resistance in hepatocytes associated with hyperinsulinemia, we show that chronic insulin exposure requires the activation of insulin receptor signaling pathways to induce hepatic cellular senescence." (PMID 35872305, 2022). "Impaired INSR endocytosis has been implicated in insulin resistance." (PMID 34921686, 2022). "Magnesium is a critical cofactor to maintain adequate enzyme function in glucose metabolism, and magnesium deficiency may interfere with insulin receptor function, leading to insulin resistance." (PMID 36576930, 2022). "Moreover, insulin resistance can be secondary to abnormalities involving insulin receptors, which are members of the tyrosine kinase family and are encoded by the INSR gene (chromosome 19p13.2)." (PMID 35740328, 2022). "Furthermore, reactive oxygen species cause insulin resistance in peripheral tissues by affecting the insulin receptor transduction pathway, ultimately resulting in decreased expression of glucose transporter type 4 in the cellular membrane." (PMID 35913467, 2022). "Insulin receptor signaling deficiency is mostly reflected in insulin resistance." (PMID 36432581, 2022). "Consistent with this, chemical inhibition or deletion of the insulin receptor specifically in adipocytes leads to severe lipodystrophy, associated with hepatosteatosis, insulin resistance accompanied by pancreatic β-cell proliferation and a metabolic syndrome phenotype." (PMID 35964946, 2022). "Mutations in the INSR gene underlie inherited syndromes of severe insulin resistance." (PMID 36465560, 2022). "This leads to an inhibition of the insulin receptor and causes insulin resistance." (PMID 35401518, 2022). "Recently, thyromegaly was shown to be present in patients with homozygous insulin receptor pathogenic variants, as well as significantly increased prevalence of thyroid nodules in patients with extreme insulin resistance (Rabson-Mandenhall and lipodystrophy syndromes)." (PMID 35158824, 2022). "INSR variants are also known to cause insulin resistance and diabetes." (PMID 35896531, 2022). "In addition, in the major glucose deposition organ fat tissue, the pro-inflammatory cytokine TNFα can directly block the insulin receptor signaling pathway to cause insulin resistance and glucose intolerance." (PMID 34276421, 2021). "All of these effects downregulate insulin receptor signaling and thereby cause insulin resistance." (PMID 34360563, 2021). "Adipocytes absorb glucose, damage insulin receptor basal protein insulin signal reception, and induce insulin resistance, and insulin resistance has been defined as a potential modifiable risk factor for Alzheimer’s disease (AD).Second, overweight reduces serum adiponectin (APN) concentration." (PMID 33663435, 2021). "Consistent with the fetal insulin hypothesis, infants with severe congenital insulin resistance secondary to loss-of-function mutations in the insulin receptor gene, INSR, have very low birthweights." (PMID 33569631, 2021).
Insulin resistance (continued). "A variety of genetic, developmental, and metabolic abnormalities that lead to disturbances in the insulin receptor signal transduction may underlie insulin resistance." (PMID 33810179, 2021). "Moreover, it has been observed that mice with isolated hepatic insulin resistance created by liver-specific disruption of the insulin receptor are markedly predisposed towards cholesterol gallstone formation." (PMID 33670445, 2021). "Phospholipids and sphingolipids are deeply involved in cell signaling and therefore their deficiency might lead to impaired insulin receptor signaling and insulin resistance." (PMID 34620173, 2021). "Finally, the improvement in insulin resistance through exercise is associated with increased expression of irisin, because it improves insulin receptor sensitization in the heart and skeletal muscle, favoring glucose uptake." (PMID 33672171, 2021). "However, obesity-induced insulin resistance is associated with reduced vascular insulin receptor expression and impaired angiogenesis, so it would be interesting to explore endothelial VEGFR2 internalization and ERK signal transduction in this setting." (PMID 34037749, 2021). "At the molecular level, insulin resistance is the consequence of insulin signaling impairment resulting from mutations or post-translation modification of the insulin receptor (IR) itself or any of its downstream effectors, including the insulin receptor substrate (IRS) proteins, PI3K, and Akt." (PMID 33562475, 2021). "Speculated CRP causes serine phosphorylation in the insulin receptor, weakening the latter's phosphatidyl inositol 3-kinase activation and leading to the development of insulin resistance." (PMID 32280714, 2020). "The hormonal changes and gene single nucleotide polymorphism of INSR may play an essential role in the occurrence of insulin resistance in patients with PCOS." (PMID 33033446, 2020). "Notably, cumulative methylation across 14 CpGs of INSR promoter in GSAT was associated with higher insulin resistance (insulin concentrations and HOMA-IR) and lower adiponectin concentrations in black women." (PMID 33133129, 2020). "Increased hepatic diglyceride levels have also been associated with insulin resistance because diglycerides modulate the affinity of the insulin receptor, through protein kinase Ce (PKCe), and our results showed that a low dose of CLA significantly reduced their concentrations." (PMID 32033223, 2020). "Another potential mechanism may be insulin resistance: patients with extreme insulin resistance have a high prevalence of thyroid nodules, and patients with a homozygous insulin receptor mutation have significantly enlarged thyroid glands." (PMID 32012985, 2020). "First, magnesium deficiency can reduce insulin receptor activity and result in insulin resistance." (PMID 32185236, 2020). "In the streptozotocin model, which made by reducing insulin receptor phosphorylation and causes insulin resistance, adult hippocampal neural stem cells proliferate less, new neuronal formation is diminished, and GLUT and insulin‐like growth factor (IGF) levels reduced." (PMID 32281722, 2020). "Therefore, it seems likely that the cellular mechanism underlying insulin resistance induced by LRP2 deletion involves a major defect in the internalization of insulin receptor at the cell surface of muscle." (PMID 32332780, 2020). "Insulin resistance has been associated with a variety of insulin receptor (IR) signaling defects." (PMID 33266015, 2020). "Studies of rare patients with mutations affecting the insulin receptor (INSR) or which interrupt signalling downstream of it have provided insight into the pathogenesis of insulin resistance and consequent dyslipidaemia or hepatic lipid accumulation in common obesity." (PMID 33233816, 2020). "Mutations in the insulin receptor cause severe forms of insulin resistance." (PMID 31686269, 2019).
Insulin resistance (continued). "It is reasonable to believe that disturbance of INSR endocytosis may affect INSR sensitivity or cause insulin resistance." (PMID 31658625, 2019). "Genetic mutations in INSR can lead to conditions with severe insulin resistance." (PMID 31658625, 2019). "The aberrant alternative splicing of insulin receptor (IR) gene and post-receptor signalling abnormalities have been associated with insulin resistance, however the precise molecular defects that cause metabolic dysfunctions are still unknown." (PMID 30901379, 2019). "Loss of the insulin receptor increases phosphorylation of tau, suggesting CNS insulin resistance could lead to an increase in this pathological mediator of Alzheimer’s disease." (PMID 31213970, 2019). "Animal models indicate that insulin resistance in older rats may be caused by a significant decrease in INSR recycling in adipocytes." (PMID 31658625, 2019). "This apparent insulin resistance may be caused by the high concentration of insulin (3 μM) used in the maintenance medium, resulting in down-regulation of insulin receptor expression at the plasma membrane." (PMID 30948643, 2019). "Indeed, many genes identified in statin-treated patients are directly linked to insulin resistance and diabetes and play defined roles in hepatic insulin receptor, AMPK and LXR/RXR signaling, clearly pointing to diabetogenic effects of statins." (PMID 31159817, 2019). "Moreover, the consumption of chokeberry and dried jujube changed the hepatic protein expression of insulin receptor, insulin receptor substrate 1, phosphoinositide 3-kinase, Akt, and catalase, which are associated with insulin resistance." (PMID 31171927, 2019). "Notably, we have shown previously in mice with inducible insulin receptor ablation that the genetically caused insulin resistance drastically increased hepatic LEPR expression that at least in part absorbed the lack of hepatic insulin action in these mice." (PMID 30224299, 2018). "This might be attributable to age-related changes to insulin receptor sensitivity at the level of the hippocampus, with age a considerable risk factor for central insulin resistance." (PMID 30619085, 2018). "However, although IRβ receptor number is important, dysregulation of downstream insulin receptor signaling is considered to be a major cause of insulin resistance." (PMID 30087656, 2018). "TNF-α is secreted by macrophages presented on stromal vascular tissue from adipose tissue and represents a pro-inflammatory adipokine, providing a central role in insulin resistance, causing the phosphorylation of the substrate-1 of the insulin receptor, and avoiding its pairing." (PMID 29497960, 2018). "Additionally, in diabetic brains p38 and JNK activation can cause insulin resistance by inhibiting the insulin receptor substrate and trigger tau hyperphosphorylation and pathological events." (PMID 29950970, 2018). "More recently, Riddle and colleagues reported that cavefish, Mexican tetra (Astyanax mexicanus) which carries a mutation in the insulin receptor lead to insulin resistance, and this phenotype is beneficial to weight gain for survival in nutrient-limited environment." (PMID 30405527, 2018). "The process of insulin resistance is associated with defects in insulin signalling downstream of insulin receptor (INSR), insulin Receptor Substrate 1/2 (IRS-1/2), Phosphoinositide 3-Kinase (PI3K)/AKT Serine/Threonine Kinase (AKT) and Glucose Transporter 4 (GLUT4)." (PMID 29050364, 2017). "At the adipocyte level, oxLDL uptake by the receptor causes the appearance of insulin-resistance by means of the interaction of multiple CD36 ligands with the serine/threonine kinase system that regulates the ligand-dependent signaling of the insulin receptor." (PMID 28729885, 2017). "Missplicing of insulin receptor (IR) gene (INSR) has been associated with insulin resistance, however, it cannot be excluded that post-receptor signalling abnormalities could also contribute to this feature in DM." (PMID 28915272, 2017).